COL1A2 (collagen type I alpha 2 chain)
Diseases named in the same sentence as COL1A2 in open-access papers (continued):
Sharing a sentence is not in itself a finding about the gene and the disease.
Peritoneal Fibrosis (3 papers, 2017 to 2023). Disorder characterized by a wide range of structural changes in PERITONEUM, resulting from fibrogenic or inflammatory processes. "C57Bl/6 has previously been identified as a good choice of mouse strain in which to study peritoneal fibrosis, with this strain exhibiting a significant peritoneal wall thickening and Col1a2 mRNA expression in response to i.p. adenovirus expressing TGFß1." (PMID 28800626, 2017). "Moreover, the immunoblotting and quantitative analysis revealed that peritoneal dialysate increased the expression of peritoneal fibrosis proteins (Fibronectin, COL1A2, and α-SMA) in rats, while Canagliflozin treatment decreased their levels." (PMID 37251320, 2023). "In TGF-β1-stimulated HPFBs, pro-fibrotic genes (COL1A1, COL1A2, ACTA2, CTGF, FN1, and TGFB1) exhibited higher expression than in controls, which are crucial targets of sildenafil and SB204741 against peritoneal fibrosis." (PMID 38322704, 2023).
sarcoma (3 papers, 2021 to 2024). A usually aggressive malignant neoplasm of the soft tissue or bone. "In sarcoma, the expression levels of ANXA1 were positively correlated with those of MMP9 (r=0.204, P=9.43e-04), COL1A2 (r=0.349, p=8.87e-09), S100A4 (r=0.574, P<0.001), VIM (r=0.48, P<0.001) and S100A11 (r=0.638, P<0.001)." (PMID 36988561, 2023).
scleroderma (3 papers, 2013 to 2023). Scleroderma is a rare autoimmune connective tissue disorder characterized by abnormal hardening of the skin and, sometimes, other organs. "Besides cartilage, the effect of lignin on the downregulation of COL1A2 may also be important in the regulation of other fibrotic diseases where the expression of type I collagen is increased such as in pulmonary, liver, and bone marrow fibrosis and scleroderma or in tumor invasion and progression." (PMID 37514430, 2023).
scrapie (3 papers, 2011 to 2014). A fatal disease of the nervous system in sheep and goats, characterized by pruritus, debility, and locomotor incoordination. "In our results, three types of collagen (COL1A2, COL3A1 and COL12A1) exhibited downregulation in sheep with natural scrapie and might be related to the loss of their neuroprotective role." (PMID 21629698, 2011). "We and others have previously reported altered expression of COL1A2, COL3A1 and COL12A1 and other ECM related genes in the CNS of sheep infected with scrapie and other prion diseases and in leukocyte-depleted splenic cells from scrapie-infected mice." (PMID 24450868, 2014). "The gene and protein expression profiles and protein distribution of six potential genetic biomarkers (i.e., CAPN6, COL1A2, COL3A1, GALA1, MT2A and MTNR1B) are presented here for both the early and terminal stages of scrapie in five different brain regions." (PMID 23497022, 2013).
viral myocarditis (3 papers, 2010 to 2022). Myocarditis that is caused by an infection with a viral agent. "CXCL12, C3, FN1, COL1A2, ACTB, VCAM1, and MMP2 were identified and finally verified as the hub genes, mainly enriched in pathways like leukocyte transendothelial migration, PI3K-Akt signaling pathway, viral myocarditis, rheumatoid arthritis, and platelet activation." (PMID 36398072, 2022).
aneurysm (2 papers, 2019 to 2025). Bulging or ballooning in an area of an artery secondary to arterial wall weakening. "MicroRNA-513b-5p downregulation in ruptured aneurysms (RA) and unruptured aneurysms (UA) targeted COL1A1 and COL1A2 genes, regulating RIP1-RIP3-MLKL and MMP pathways to enhance cell death and apoptosis." (PMID 41342741, 2025).
Bruck syndrome (2 papers, 2014 to 2016). Bruck syndrome is characterized by the association of osteogenesis imperfecta and congenital joint contractures. "Studies of Bruck syndrome have found normal secretion of collagen 1 in three families, whereas no mutations have been detected in the COL1A1 and COL1A2 genes." (PMID 24767406, 2014).
chondrodysplasia (2 papers, 2021 to 2022). "In addition to variants in COL1A1 and COL1A2 associated with OI, many pathogenic variants in COL2A1 and COL10A1 are linked to chondrodysplasias." (PMID 33672767, 2021). "Since carbamazepine (CBZ) both stimulates autophagy of misfolded collagen X and improves skeletal pathology in a metaphyseal chondrodysplasia model, we tested the effect of CBZ on bone structure and strength in 3‐week‐old male OI Col1a2+/p.G610C and control mice." (PMID 35701367, 2022).
Duchenne muscular dystrophy (2 papers, 2020 to 2024). Duchenne muscular dystrophy (DMD) is a neuromuscular disease characterized by rapidly progressive muscle weakness and wasting due to degeneration of skeletal, smooth and cardiac muscle. "COL1A2, FBN1 and FN1 may be novel biomarkers for DMD, and the siRNAs designed in our study were help to develop adjunctive therapy for Duchenne muscular dystrophy." (PMID 38762732, 2024).
Dupuytren's disease (2 papers, 2018 to 2021). "COL1A2 is under-expressed in Polycystic Kidney Disease but over-expressed in IPF, IgG4-related and Dupuytren’s Disease." (PMID 33826640, 2021).
esophageal squamous cell carcinoma (2 papers, 2013 to 2020). Esophageal squamous cell carcinoma (ESCC) is a type of esophageal carcinoma (EC) that can affect any part of the esophagus, but is usually located in the upper or middle third. "Some of the differentially-expressed genes reported in GCA were also dysregulated in a similar pattern as esophageal squamous cell carcinomas (ESCC) examined from this same high-risk population, such as CDC25B and COL1A2." (PMID 23717493, 2013). "Other authors have also suggested a tandem effect with COL1A2 in NSCLC and esophageal squamous cell carcinomas." (PMID 33062455, 2020).
glomerulosclerosis (2 papers, 2019 to 2023). A hardening of the kidney glomerulus caused by scarring of the blood vessels. "In a glomerulosclerosis model, HIF-1α was shown to form a complex with phophoSMAD3 at the COL1A2 promoter, inducing Col-1 synthesis." (PMID 29603016, 2019).
head and neck squamous cell carcinoma (2 papers, 2020 to 2023). A squamous cell carcinoma that arises from any of the following anatomic sites: lip and oral cavity, nasal cavity, paranasal sinuses, pharynx, larynx, and salivary glands. "Experimental validation using qPCR and immunofluorescence revealed CAF-specific higher expression of TIMP-1 and COL1A2 as compared to other markers in 5 novel CAF cells, derived from patients of diverse gender, habits and different locations of head and neck squamous cell carcinoma (HNSC)." (PMID 37626157, 2023).
hearing loss (2 papers, 2011 to 2021). "Several collagen genes (COL1A1, COL1A2, COL2A1, COL4A3, COL4A4, COL4A5, COL11A1, and COL11A2) are associated with hereditary syndromic hearing loss." (PMID 33848312, 2021).
hypopharyngeal cancer (2 papers, 2018 to 2023). Carcinoma, predominantly squamous cell, arising from the epithelial cells of the hypopharynx. "In the multivariate Cox proportional hazards analysis, the methylation of COL1A2 and VEGFR1 was associated with poor survival for hypopharyngeal cancer, with hazard ratios: 3.19; p = 0.009 and 3.07; p = 0.014, respectively." (PMID 29361757, 2018). "In patients with hypopharyngeal cancers, methylation of COL1A2 and VEGFR1 promoters correlated positively with recurrence (odds ratio (OR) = 3.19, 95% CI: 1.33–7.66, p = 0.009 and OR = 3.07, 95% CI: 1.25–7.49, p = 0.014, respectively)." (PMID 29361757, 2018).
lentivirus infection (2 papers, 2009 to 2015). Virus diseases caused by the Lentivirus genus. "TGFβ1-induced COL1A2, PAI-1, and CTGF mRNA levels were also partially inhibited by shSET7/9 lentivirus infection, whereas no significant increase and decrease induced by TGFβ1 and shSET7/9, respectively, was observed in the GCD2-homozygous cells." (PMID 26553048, 2015).
liver cirrhosis (2 papers, 2018 to 2025). "The roles of COL1A1 and COL1A2 in liver cirrhosis were confirmed in the stained samples, and higher expression levels were found in the advanced stages of liver cirrhosis." (PMID 41223189, 2025). "The mRNA and protein levels of α-SMA and COL1A2 were significantly up-regulated in the tissue of rats with liver cirrhosis compared to those in normal animals." (PMID 29416678, 2018).
mitral valve disease (2 papers, 2016 to 2024). "The deletion of COL1A2 gene might be the primary cause for the development of mitral valve prolapse identified in our patient." (PMID 27291887, 2016).
non-alcoholic fatty liver disease (2 papers, 2020 to 2023). "Intriguingly, our previous studies showed that EGCG treatment shared four common collagen-related genes Col1a1, Col1a2, Col3a1 and Col6a3 with atorvastatin treatment in non-alcoholic fatty liver diseases." (PMID 32290071, 2020).
Oligodontia (2 papers, 2020 to 2021). The absence of six or more teeth from the normal series by a failure to develop. "Seventy-five percent of the individuals presenting with oligodontia harbored mutations in COL1A1 and COL1A2 that were predicted to cause qualitatively changed protein." (PMID 32234057, 2020). "Our findings suggest that mutations in COL1A1, COL1A2, and CREB3L1 may cause hypodontia and oligodontia in OI." (PMID 32234057, 2020). "Except for the rare pathogenic variants in COL1A1, COL1A2, and CREB3L1, we were unable to identify any other pathogenic variant in a shared gene in the cohort that could explain the phenotype of oligodontia." (PMID 32234057, 2020).
Parkinson disease (2 papers, 2013 to 2025). A progressive degenerative disorder of the central nervous system characterized by loss of dopamine producing neurons in the substantia nigra and the presence of Lewy bodies in the substantia nigra and locus coeruleus. "The other markers (i.e., CAPN6, COL1A2, COL3A1, GALA1 and MTNR1B) belong to gene families with a known role in other neurodegenerative diseases, such as Alzheimer’s or Parkinson’s disease in humans." (PMID 23497022, 2013).
triple-negative breast carcinoma (2 papers, 2021 to 2025). An invasive breast carcinoma which is negative for expression of estrogen receptor (ER), progesterone receptor (PR), and human epidermal growth factor receptor 2 (HER2). "Collagen subunit proteins COL1A1, COL1A2, COL3A1, and COL11A1 have been related to triple-negative breast cancer: COL1A1 expression is elevated in TNBC tissues and is associated with increased tumor stiffness, promoting cancer progression and metastasis, making it an independent prognostic factor." (PMID 40867231, 2025).
abscesses (1 paper, 2025). "COL1A2 is one of the principal components of the ECM and may play a role in encapsulating the abscesses as part of the fibrotic walls." (PMID 40489480, 2025).
androgenetic alopecia (1 paper, 2024). "Furthermore, Zhou revealed that COL1A2 may also function in androgenetic alopecia." (PMID 38773419, 2024).
Aortic dissection (1 paper, 2019). Aortic dissection refers to a tear in the intimal layer of the aorta causing a separation between the intima and the medial layers of the aorta. "VUS of ACTA2 emerged as significantly associated with aortic dissection while COL1A1 and COL1A2 VUS significantly influenced hyperlaxity." (PMID 31536524, 2019).
bladder tumor (1 paper, 2025). "Our integrative single-cell transcriptomic analysis reveals a previously unappreciated spatial orchestration of the COL1A2–ECM–FAK axis within the bladder tumor microenvironment." (PMID 41561769, 2025).
bone metabolism disorders (1 paper, 2008). "Highly connected sub-networks of proteins associated with CKD, CVDs or bone metabolism disorders were detected involving proteins like collagens (COL1A1, COL1A2), fibronectin, transforming growth factor-β1, or components of fibrinogen (FG-α, FG-β, FG-γ)." (PMID 18266955, 2008).
brain tumours (1 paper, 2022). "we have reported five co-regulated clusters via seven important co-expression genes (COL1A2, LUM, SPARC, THBS2, IL1B, CXCL8, THY1) interacting between five clusters of the brain tumours." (PMID 35045088, 2022).
Camurati-Engelmann disease (1 paper, 2021). Camurati-Englemann disease (CED) is a rare, clinically variable bone dysplasia syndrome characterized by hyperostosis of the long bones, skull, spine and pelvis, associated with severe pain in the extremities, a wide-based waddling gait, joint contractures, muscle weakness and easy fatigability. "A total of 7/47 probands suspected with OI carried variants in 6 disease-causing genes, namely, 1 IFITM5, 1 CRTAP, 2 BMP1, 1 PLS3, and 1 COL1A2 (c.432 + 4_432 + 7delAGTA was ignored previously), and 1 case of Camurati-Engelmann disease with pathogenic variants in TGFβ-1, which was misdiagnosed." (PMID 34557487, 2021).
carcinoid (1 paper, 2021). "The expression of COL1A2, COL3A1, COL5A2, ITGA5, and ITGB1 in SCLC, LCNEC, and typical carcinoid samples in the GSE1037 profile, as compared with normal samples, were determined using a GEO2R online analyzer (log FC>2 and adjusted P<0.05) and then compared to the data from our cohort." (PMID 34458147, 2021).
cervical squamous cell carcinoma (1 paper, 2023). A squamous cell carcinoma arising from the cervical epithelium. "POSTN + fibroblasts showed high expression levels of several ECM remodeling genes (MMP11, CTHRC1, COL1A1, COL1A2, COL3A1, COL10A1, and COL11A1) and enriched signatures of ECM, which were consistent with the previously reported matrix CAFs (mCAFs) in cervical squamous cell carcinoma (CESC)." (PMID 37833788, 2023).
Chronic colitis (1 paper, 2023). A chronic inflammatory disease of the large intestine (colon, cecum and rectum). "DSS-induced chronic colitis attenuated biliary septal fibrosis, which may be attributed to less BA accumulation mediated inhibition of activated HSCs (Col1a1, Col1a2, Col3a1 and Timp1) without affecting PFs in Mdr2−/− mice." (PMID 37280200, 2023).
chronic kidney disease (1 paper, 2026). Impairment of the renal function secondary to chronic kidney damage persisting for three or more months. "RNA‐seq analysis of kidney organoids post 24 h heat stress at 41°C revealed no significant upregulation of COL1A1 or COL1A2, the genes encoding type I collagen, a key component of the fibrotic matrix in chronic kidney disease." (PMID 41573374, 2026).
colorectal adenocarcinoma (1 paper, 2025). The most common type of colorectal carcinoma. "The TIMER 2.0 database shows a positive correlation between PTN, THBS2, and COL1A2 expression and immune cell infiltration in CAFs of colorectal adenocarcinoma (COAD) and rectal adenocarcinoma (READ)." (PMID 40242441, 2025).
cystic kidneys (1 paper, 2022). "This was associated with an increased mRNA expression of Il1b, Tnf, Mcp1, Fn1, and Col1a2 genes in the cystic kidneys of Pkd1-miR Tg mice." (PMID 35955634, 2022).
diabetic cardiomyopathy (1 paper, 2022). Diabetic cardiomyopathy is a disorder of the heart muscle in people with diabetes. "The salient findings from the present study support that Cyp1a1, a significantly upregulated DEG, has the highest connectivity in the PPI interaction network among the top five hub genes (Cyp1a1, Cyp2e1, Col1a1, Col3a1, Col1a2) to affect the cardiac function in STZ-induced diabetic cardiomyopathy." (PMID 35387435, 2022).
disc degeneration (1 paper, 2025). "OI patients with COL1A1/COL1A2 mutations may have heightened susceptibility to disc herniation despite modest disc degeneration." (PMID 40760627, 2025).
endometriosis (1 paper, 2023). The growth of functional endometrial tissue in anatomic sites outside the uterine body. "In endometriosis, this condition has been related to the aberrant transcriptional activation of Col1a1 and Col1a2 genes, proving to be critical factors for endometrial receptivity." (PMID 36830911, 2023).
experimental autoimmune encephalomyelitis (1 paper, 2023). An autoimmune demyelinating disease of the central nervous system that is produced experimentally in animals by the injection of homogenized brain or spinal cord in Freund's adjuvant. "In line, the participation of CNS fibroblasts, but not PCs or vSMCs, in fibrotic scar formation was demonstrated in an experimental autoimmune encephalomyelitis model using three different inducible reporter mouse lines (NG2, aSMA, and Col1a2)." (PMID 37143930, 2023).
fatty liver (1 paper, 2018). "To further determine which genes might play a significant role in the progression of fatty liver, we used real-time qPCR to detect the expression of 8 DEGs using clinical samples, including CD24, PZP, COL1A1, COL1A2, LUM, VCAN, THBS2 and EPHA3." (PMID 29769552, 2018).
focal segmental glomerulosclerosis (1 paper, 2017). A renal disorder characterized by sclerotic lesions in the glomeruli. "In anti-Tac(Fv)-PE38(LMB2)-induced podocyte injury and focal segmental glomerulosclerosis model, HIF-1α has been reported to increase and bind to the HRE of collagen type I alpha 2 chain (COL1A2) promotor." (PMID 28468297, 2017).
ganglioglioma (1 paper, 2023). A well differentiated, slow growing neuroepithelial neoplasm composed of neoplastic, mature ganglion cells and neoplastic glial cells. "Co-expression of CD34, PAX6, SOX2, and MSI1 (after stringent counter selection against vascular cells using PECAM1, VWF, DCN, and COL1A2), was particularly strongly associated with ganglioglioma neoplastic cell stemness." (PMID 36966348, 2023).
gliosarcoma (1 paper, 2019). A rare histological variant of glioblastoma (WHO grade IV) characterized by a biphasic tissue pattern with alternating areas displaying glial and mesenchymal differentiation (WHO). "When compared to GBMs, gliosarcomas show up-regulation of some genes, ranging up to a 6-fold difference on a log2-scale and most top differentiating genes encode collagens (COL1A1, COL6A1, COL6A2, COL6A3, COL1A2, COL3A1)." (PMID 30818875, 2019).
Histiocytosis (1 paper, 2024). An excessive number of histiocytes (tissue macrophages). "The COL1A2-ALK fusion has been found in ALK-positive histiocytosis." (PMID 38476985, 2024).
holoprosencephaly (1 paper, 2019). Holoprosencephaly (HPE) is a complex brain malformation resulting from incomplete cleavage of the prosencephalon, occurring between the 18th and 28th day of gestation, and affecting both the forebrain and face, which results in neurological manifestations and facial anomalies of variable severity. "Next-generation sequencing demonstrated that the family had compound heterozygous mutations in COL1A1 and COL1A2, with no known mutations related to PSIS, pituitary hormone deficiency (PHD), or holoprosencephaly (HPE)." (PMID 30984112, 2019).
influenza (1 paper, 2025). An acute viral infection of the respiratory tract, occurring in isolated cases, in epidemics, or in pandemics; it is caused by serologically different strains of viruses (influenzaviruses) designated A, B, and C, has a 3-day incubation period, and usually lasts for 3 to 10 days. "Col1a2/Vcan−/− and WT mice were infected with 20 PFU of IAV and monitored for up to 15 dpi to investigate the impact of mesenchymal-derived versican deficiency on influenza infection and disease." (PMID 40766376, 2025). "Influenza disease severity and viral load were unaltered throughout IAV infection in Col1a2/Vcan−/− mice." (PMID 40766376, 2025).
inguinal herniae (1 paper, 2016). "Mutations of the COL1A2 gene have been related to bilateral inguinal herniae and wormian bones in Ehlers–Danlos syndrome type VIIB." (PMID 27291887, 2016).
keratinocyte carcinoma (1 paper, 2023). A skin cancer arising from the keratin-producing cells of the epidermis. "Importantly, Col1a2;hMMP1 and Col1a2-hCCN1 mice exhibit an enhanced preponderance of keratinocyte cancer in mouse models of skin carcinogenesis: cutaneous two-stage chemical carcinogenesis and inducible HRas-oncogene-driven tumors." (PMID 38002296, 2023).